TNC (tenascin C)
Diseases named in the same sentence as TNC in open-access papers (continued):
Sharing a sentence is not in itself a finding about the gene and the disease.
ependymoma (4 papers, 2016 to 2020). A WHO grade II, slow growing tumor of children and young adults, usually located intraventricularly. "TNC expression by immunohistochemistry (IHC) has been shown, specifically in ependymomas, to be associated with higher grade and inferior event-free survival in small retrospective series." (PMID 28617804, 2017). "TNC has been described as candidate gene for ependymoma progression in posterior fossa tumors with gain of 9pter." (PMID 27550150, 2016). "The aim of this study was to analyze the status of chromosome 1q, TNC, LAMA2, and NELL2 expression in a series of pediatric PF ependymomas in terms of their frequency, associations among themselves and clinical parameters, as well as their prognostic impact." (PMID 27550150, 2016). "Previous studies in pediatric ependymoma reported, at recurrence, frequent gains of chromosome 9q33-34 region, i.e. the genomic region of NOTCH1 and Tenascin-C (TNC), associated with the overexpression of TNC." (PMID 28617804, 2017). "TNC expression was found in 94 % of posterior fossa Group A tumors and only in 11 % of posterior fossa Group B tumors and thus, seems to be a marker for the majority of PF Group A ependymomas." (PMID 27550150, 2016). "Therefore, we have analyzed the status of chromosome 1q, TNC, LAMA2, and NELL2 expression in a series of pediatric PF ependymomas in terms of their frequency, associations among themselves, and clinical parameters, as well as their prognostic impact." (PMID 27550150, 2016).
head and neck squamous cell carcinoma (4 papers, 2017 to 2023). A squamous cell carcinoma that arises from any of the following anatomic sites: lip and oral cavity, nasal cavity, paranasal sinuses, pharynx, larynx, and salivary glands. "To determine the expression and relative localization of FN and TNC in the vasculature of human tumours, we performed immunostaining on adjacent sections of head and neck squamous cell carcinomas (HNSCC)." (PMID 28986537, 2017). "Besides, miR-150-5p and − 3p targets ITGA3 (integrin alpha 3), ITGA6 (integrin alpha 6), and TNC (tenascin C) in head and neck squamous cell carcinoma." (PMID 37924077, 2023).
invasive breast carcinoma (4 papers, 2017 to 2020). A carcinoma that infiltrates the breast parenchyma. "TNC knockdown in invasive breast cancer cells was shown to reduce proliferation and invasion." (PMID 29728077, 2018). "As a next step we compared the expression levels of tenascin genes (TNC, TNN, TNR, TNXB) in invasive breast cancer using GEPIA program." (PMID 32817625, 2020).
ischemia (4 papers, 2015 to 2022). A hypoperfusion of the BLOOD through an organ or tissue caused by a PATHOLOGIC CONSTRICTION or obstruction of its BLOOD VESSELS, or an absence of BLOOD CIRCULATION. "Fibronectin was significantly elevated in the retina following ischemia, while laminin, tenascin-C and aggrecan showed enhanced immunoreactivity in the optic nerve after ischemia, indicating their regulatory role during neurodegeneration." (PMID 35269741, 2022). "Regarding fibronectin, significantly elevated mRNA and protein levels were observed in the retina following ischemia, while laminin and tenascin-C showed enhanced immunoreactivity in the optic nerve after ischemia." (PMID 28262779, 2017). "Remodeling of tenascin-C was also reported in other tissues following ischemia." (PMID 28262779, 2017).
liver cancer (4 papers, 2019 to 2025). An epithelial or non-epithelial malignant neoplasm that arises from the liver. "Knockdown of TNC inhibited CREB5-induced promotion of liver cancer cell migration, invasion, and EMT, which further indicated that CREB5 plays a role in promoting EMT through TNC." (PMID 39915455, 2025). "Although this study identified that CREB5, targeted by ERS-related SE, promotes EMT in liver cancer cells by directly activating the transcription of TNC, several questions remain." (PMID 39915455, 2025). "In summary, our findings suggest that ERS activation promotes EMT in liver cancer cells via SE-mediated upregulation of the CREB5/TNC pathway." (PMID 39915455, 2025). "CREB5 directly bound to the tenascin-C (TNC) promoter to induce EMT in liver cancer cells, which ultimately enhanced invasion and metastasis." (PMID 39915455, 2025). "Also, CREB5 promoted epithelial-mesenchymal transition (EMT) in liver cancer cells by directly binding to the promoter region of tenascin-C (TNC) and upregulating its transcription." (PMID 40606603, 2025). "Mechanistically, CREB5 upregulates the transcription of tenascin-C (TNC) by directly binding to its promoter region, thereby promoting EMT in liver cancer cells." (PMID 39915455, 2025). "Moreover, dual-luciferase and ChIP-qPCR assays verified that CREB5 binds to the TNC promoter, promotes transcription of TNC, and plays a role in inducing EMT in liver cancer cells." (PMID 39915455, 2025). "Given that CREB5 is a transcription factor that regulates TNC in liver cancer cells, we performed a dual-luciferase reporter assay to investigate whether CREB5 increases TNC promoter activity." (PMID 39915455, 2025). "Myofibroblasts (hepatic myofibroblasts) and CAFs (fibroblasts isolated from liver cancer patients) expressing α-SMA and Tenascin-C show similar apoptosis signaling compared to fibroblasts not expressing α-SMA and Tenascin-C (defined by the authors as quiescent fibroblasts)." (PMID 30841909, 2019).
lung adenocarcinoma (4 papers, 2020 to 2024). A carcinoma that arises from the lung and is characterized by the presence of malignant glandular epithelial cells. "In lung adenocarcinoma, the expression of TnC is strongly downregulated compared to that in normal lung tissues, and downregulation of TnC is strongly correlated with increased mortality." (PMID 38542091, 2024). "As the increased levels of THSB2, VCAN, and TNC on sEVs were found to indicate lung adenocarcinoma patients, we combined these biomarkers and explored their usage as a signature in identifying malignant and benign lung lesions." (PMID 36394090, 2022). "Tenascin-C, like its binding partner fibronectin, is significantly upregulated in fibrotic lungs and in lung adenocarcinoma raising the notion of a potentially overlapping mechanistic contribution to these disease processes." (PMID 33014869, 2020).
malignant glioma (4 papers, 2019 to 2022). A grade III or grade IV glioma arising from the central nervous system. "In contrast, TNC is implicated in malignant glioma progression, including neovascularization, proliferation, invasiveness, and immunomodulation." (PMID 36033448, 2022). "Radiolabeled antibodies specific to distinct domains of TNC have been tested for the treatment of malignant gliomas in clinical studies." (PMID 36033448, 2022). "ECMs of malignant gliomas include vitronectin, proteoglycan, collagen I and IV, osteopontin and tenascin C (TNC)." (PMID 32875951, 2020). "TNC overexpression is reported in adult high grade glioma (HGG) and has been explored as a biomarker of disease and potential therapeutic target." (PMID 31092287, 2019).
medulloblastoma (4 papers, 2011 to 2025). A malignant, invasive embryonal neoplasm arising from the cerebellum. "There is a report that TNC protein and its partner integrins mediate adhesion of medulloblastoma cells to leptomeninges and facilitate tumor seeding." (PMID 23768125, 2013).
squamous cell carcinoma (4 papers, 2013 to 2020). A carcinoma arising from squamous epithelial cells. "The large splice variant of tenascin C is specifically expressed in tumors and expression levels increase with grade of malignancy in many cancer types including brain, lung, and squamous cell cancer." (PMID 26539408, 2015). "Fibroblasts enhance the invasion of squamous cell carcinoma cells in a similar way, with both matrix ‘holes’ and fibroblast deposition of the matrix components fibronectin and tenascin-C implicated as potential stimulatory mediators of epithelial invasion." (PMID 23939832, 2013). "Anti-tenascin-C and anti-tenascin-W both immunolabel the stroma of poorly (n = 3), moderately (n = 4) and well differentiated adenocarcinomas (n = 2), as well as the stroma of a single squamous cell carcinoma and a single mucinous carcinoma." (PMID 33692777, 2020).
Stroke (4 papers, 2020 to 2023). Sudden impairment of blood flow to a part of the brain due to occlusion or rupture of an artery to the brain. "Similarly, tenascin-C is found in the extracellular matrix and is associated with poor prognosis in stroke due to its neuroinflammatory properties, while CRP, a commonly used clinical marker for non-specific general inflammation, did not correlate with futile recanalization." (PMID 38089974, 2023). "Tenascin-C is a potential biomarker for predicting the occurrence and severity of coronary atherosclerosis as well as stroke severity and outcomes." (PMID 35493201, 2022). "In this review, we focus on a MCP tenascin-C (TNC) involved in neuroinflammation following stroke, and highlight current evidence for its use as a clinical biomarker and a therapeutic target." (PMID 33552066, 2020). "Currently, a matricellular protein tenascin-C (TNC) is considered to be an important inducer to promote neuroinflammatory cascades and the resultant pathology in stroke." (PMID 33552066, 2020). "Accumulating evidence suggests that many types of MCPs, such as TNC, periostin, galectin-3, and osteopontin, contribute to aggravation or improvement of neuroinflammation in stroke at least partly by influencing the expression of each other." (PMID 33552066, 2020). "Due to the upregulation of TnC following aneurysmal subarachnoid hemorrhage and the possibility to easily measure its concentration in cerebrospinal fluid or plasma by ELISA, TnC was proposed as a biomarker candidate of stroke." (PMID 38107409, 2023). "In addition, TNC upregulation after stroke contributes to activation of signaling transduction and exacerbation of secondary brain injuries through the toll-like receptor signaling pathway." (PMID 35493201, 2022). "Although the mechanisms of osteopontin’s anti-TNC effects remain poorly understood in stroke, osteopontin and TNC share some receptors such as RGD-dependent integrins, and therefore at least partly competitive inhibition may be the mechanism." (PMID 33552066, 2020). "TNC directly binds to other MCPs periostin and galectin-3, and may regulate the expression levels of each other in stroke, playing diverse roles." (PMID 33552066, 2020). "Recent findings have suggested that TnC in pathological states may have additional functions, as it is an important inducer of neuroinflammatory cascades, and plays a significant role in the pathogenesis of stroke and brain injury, as well as in the subsequent repair processes." (PMID 38107409, 2023).
subarachnoid hemorrhage (4 papers, 2020 to 2023). A serious neurological disorder characterized by intracranial hemorrhage into the subarachnoid space. "Tenascin-C is increased after subarachnoid hemorrhage and may cause cytotoxic and vasogenic edema." (PMID 38025264, 2023).
thyroid cancer (4 papers, 2010 to 2025). "TNC expression has been implicated as a driver of metastasis, so we further assessed the association between TNC and metastasis in our thyroid cancer cohorts." (PMID 39951495, 2025). "TNC expression was associated with aggressive thyroid cancer behavior, including anaplastic histology, extrathyroidal extension, and metastasis." (PMID 39951495, 2025). "We demonstrate that TNC expression is upregulated in thyroid cancer cells along the tumor's invasive edge and within intravascular spaces." (PMID 39951495, 2025). "Our data demonstrate that TNC expression is tightly regulated in thyroid cancer, as it is expressed by tumor cells along the leading edge and within areas of intravascular invasion." (PMID 39951495, 2025). "Here, we investigated the expression of TNC in thyroid cancer and its role in amplifying ligand-driven Wnt signaling." (PMID 39951495, 2025). "We show here that within thyroid cancer there is an interaction between TNC and Wnt-2 that leads to pathway activation." (PMID 39951495, 2025). "Here, we investigated the role of TNC in facilitating ligand-dependent Wnt signaling in thyroid cancer." (PMID 39951495, 2025). "In this study, using multiple large patient cohorts, in vitro models, and in vivo mouse models, we identified TNC as an important modulator of Wnt signaling in thyroid cancer." (PMID 39951495, 2025). "We next investigated TNC expression in the more aggressive thyroid cancer, ATC." (PMID 39951495, 2025). "Based on our in vivo animal studies, we speculate that this potentiation of Wnt signaling by TNC plays an important role in driving thyroid cancer invasion and metastasis." (PMID 39951495, 2025). "Additionally, TNC is known to have several different splicing events, so we evaluated the different isoforms of TNC present in thyroid cancer." (PMID 39951495, 2025). "In addition, targeting TNC may lead to therapeutic advances for some of the most aggressive and lethal thyroid cancers." (PMID 39951495, 2025). "However, our understanding of TNC expression and TNC-Wnt crosstalk in thyroid cancers is limited." (PMID 39951495, 2025). "Taken together, TNC expression is upregulated in thyroid cancer compared to normal tissue." (PMID 39951495, 2025). "Furthermore, other L/R pairs identified in our analysis, namely INHBB/ACVR1 and TNC/ANXA2, have been shown to be involved in invasiveness of other solid tumors, and as they have not yet been studied in thyroid cancer, warrant further investigation in this context." (PMID 20877637, 2010).
ulcerative colitis (4 papers, 2021 to 2025). An inflammatory bowel disease involving the mucosal surface of the large intestine and rectum. "The identified immune biomarkers (CCL18, DUOX2, GREM1, LCN2, and TNC) demonstrated strong diagnostic efficacy and are key immune genes for ulcerative colitis (UC)." (PMID 40584713, 2025). "The expression levels of core immune genes including CCL18, DUOX2, GREM1, LCN2, and TNC in ulcerative colitis models were detected by fluorescence q-PCR." (PMID 40584713, 2025). "This increase of tenascin-C in animal models is consistent with the increased tenascin-C detected in inflamed human ulcerative colitis colon tissue." (PMID 35669358, 2022). "Therefore, we stained human colon tissue from an ulcerative colitis (UC) patient and noticed a staining pattern that resembled published TNC expression in this tissue." (PMID 33790905, 2021).
adenoma (3 papers, 2015 to 2022). A neoplasm arising from the epithelium. "We showed that genes ANLN, CDK1, ECT2, and TNC were associated with adenoma progression to carcinoma, ANLN and PDGFD with development of metastases, while genes ANLN, CDK1, ECT2, and PDGFD were associated with the level of malignancy." (PMID 36362041, 2022). "Although we identified downregulation of TNC in adenomas when compared to normal mucosa, we observed upregulation when comparing adenoma with early carcinoma to adenoma." (PMID 36362041, 2022). "ANLN, CDK1, ECT2, and TNC were differentially expressed between adenoma and adenoma with early carcinoma." (PMID 36362041, 2022). "Statistically significant results in adenomas include 12.4-fold downregulation of TNC (p ≤ 0.001), 9.4-fold downregulation of TNXB (p ≤ 0.001), and 6.0-fold upregulation of ECT2 (p ≤ 0.001)." (PMID 36362041, 2022). "Expression of the ECM molecule Tenascin-C (Tn-C), most likely produced by myofibroblasts, increased from benign adenomas to malignant carcinomas, and with signs of invasion and metastasis." (PMID 31921858, 2019). "Consistent with this, the Wnt target genes MMP7 and Tenascin-C, which are expressed at high levels in benign human adenomas and early colon cancer stages, were upregulated in pre-malignant tissue of gpA33ΔN-Bcat mice." (PMID 26398937, 2015). "We identified statistically significant differences between the adenoma and adenoma with early carcinoma for ANLN (p ≤ 0.001), CDK1 (p ≤ 0.05), ECT2 (p ≤ 0.01), and TNC (p ≤ 0.05)." (PMID 36362041, 2022). "The genes TNC, CDK1, ANLN, and ECT2 were significantly upregulated in adenoma with early carcinoma when compared to adenoma and can be considered as potential biomarkers for malignant transformation." (PMID 36362041, 2022).
ankylosing spondylitis (3 papers, 2023 to 2025). An autoimmune chronic inflammatory disorder characterized by inflammation in the vertebral joints of the spine and sacroiliac joints. "Tenascin-C (TNC), a large extracellular matrix glycoprotein, is upregulated in ankylosing spondylitis (AS) and other inflammatory conditions." (PMID 39781450, 2025).
chronic hepatitis C (3 papers, 2010 to 2021). "More specifically, serum levels of large splice variants of tenascin-C were proposed as useful markers of the inflammatory activity during chronic hepatitis C and in particular of the degree of piecemeal necrosis." (PMID 34065048, 2021). "A chronic liver injury leads to the activation of HSCs, with concomitant enhanced secretion of tenascin-C in chronic hepatitis C." (PMID 34065048, 2021). "Tenascin C levels are significantly high in patients with chronic hepatitis C, liver cirrhosis, and HCC." (PMID 33322158, 2020). "Furthermore, tenascin-C is up-regulated in chronic hepatitis C, and its expression in peritumoral activated stellate cells in HCC associates with poor clinical prognosis." (PMID 21209952, 2010).
diabetic kidney disease (3 papers, 2024 to 2026). Progressive kidney disorder caused by vascular damage to the glomerular capillaries, in patients with diabetes mellitus. "Metformin treatment was reported to relieve the processes of inflammation and fibrosis in individuals with diabetic kidney disease by reducing the levels of the Tenascin-C, p-NF-κB (p65), connective tissue growth factor, and fibronectin proteins." (PMID 39033184, 2024).
endometriosis (3 papers, 2013 to 2021). The growth of functional endometrial tissue in anatomic sites outside the uterine body. "One such protein, tenascin C (TNC), was reported to be regulated across the menstrual cycle and aberrantly in endometriosis." (PMID 30992697, 2019). "Our data suggest that its cyclic expression is lost in the endometrium of endometriosis patients, and whilst we did not observe TNC overexpression in ectopic lesions, its increased expression may promote adhesion and invasion of endometrial cells at ectopic sites." (PMID 30992697, 2019).
esophageal squamous cell carcinoma (3 papers, 2016 to 2024). Esophageal squamous cell carcinoma (ESCC) is a type of esophageal carcinoma (EC) that can affect any part of the esophagus, but is usually located in the upper or middle third. "The association between expression of Tenascin-C and that of cancer associated fibroblast markers in esophageal squamous cell carcinoma stromal tissues." (PMID 26731558, 2016). "The present finding that elevated TNC expression was significantly correlated with poor outcomes in CRC is consistent with the results of previous studies in patients with esophageal squamous cell carcinoma." (PMID 32322169, 2020). "Multivariate Cox proportional hazard model analysis by classification of Tenascin-C expression in esophageal squamous cell carcinoma." (PMID 26731558, 2016). "Comparison of clinicopathologic characteristics according to Tenascin-C expression in esophageal squamous cell carcinoma tissues." (PMID 26731558, 2016). "The overall survival and disease free survival rates of patients with expression of Tenascin-C (TNC) and cancer associated fibroblast markers in esophageal squamous cell carcinoma stromal tissues." (PMID 26731558, 2016). "Univariate Cox proportional hazard model analysis by classification of Tenascin-C expression in esophageal squamous cell carcinoma." (PMID 26731558, 2016). "We explored the clinicopathological significance of Tenascin-C as a prognostic determinant of esophageal squamous cell carcinoma (ESCC)." (PMID 26731558, 2016).